INS (insulin)
Diseases named in the same sentence as INS in open-access papers (continued):
Sharing a sentence is not in itself a finding about the gene and the disease.
lipid metabolism disorders (continued). "CCSKO also decreased fat accumulation in adipose tissue, reduced body weight, improved blood and liver lipid levels, increased insulin sensitivity, and improved dyslipidemia and lipid metabolic disorders in high-fat diet-induced obese rats." (PMID 36673385, 2023). "JUK is activated, which can downregulate insulin signal transduction, reduce the sensitivity of surrounding tissue cells to insulin, and lead to glucose and lipid metabolism disorders." (PMID 36452059, 2022). "They showed NC was strongly correlated with increased insulin levels and lipid metabolism disorders (elevated triglyceride and decreased HDL)." (PMID 35501838, 2022). "It has a significant effect on improving lipid metabolism disorders, increasing insulin sensitivity, and improving IR in obese children and adolescents." (PMID 36531167, 2022). "CRP can not only aggravates the inflammatory reaction, but also reduces the sensitivity of tissue cells to insulin, and play a certain role in lipid metabolism disorder." (PMID 35784937, 2022). "Insufficiency of insulin secretion and/or function defect characteristic of diabetic patients are mainly manifested as glucose and lipid metabolism disorders." (PMID 34423045, 2021). "A high-fat diet resulted in glucose and lipid metabolism disorders with higher levels of visceral fat rate, insulin-resistance indices, and leptin." (PMID 34238228, 2021). "In the current study, we show that FAF1 overexpression dramatically exacerbates glucose and lipid metabolic disorder, as well as insulin resistance by contributing to JNK activation in hepatocytes." (PMID 33510836, 2021). "The differentially expressed genes in KK-Ay mice are mainly related to the amino acid metabolism pathway disorder, insulin secretion abnormality, glucose and lipid metabolism disorder and impaired coagulation function observed in the mice." (PMID 32266256, 2020). "Based on previous research, this regimen produces a T2DM model rat exhibiting a pathophysiological high blood glucose, insulin resistance and lipid metabolism disorder." (PMID 30390707, 2018). "As a result, the deactivation/dephosphorylation of IRS1 would lead to the impairment of insulin effect, such as the glucose metabolism disorder and lipid metabolism disorder." (PMID 27054886, 2016). "One is insulin sensitization agent such as Pioglitazone, Rosiglitazone; the other is correcting the lipid metabolism disorders agent such as Repaglinide, Telmisartan." (PMID 27191267, 2016). "These pathways play crucial roles in inflammation, lipid metabolism disorders, oxidative stress, and insulin sensitivity regulation, further supporting the potential mechanism by which BHEE synergistically intervenes in the pathological progression of HLP through multiple pathways." (PMID 41304686, 2025). "The FoxO protein, as a downstream protein of the insulin pathway, may be the key molecule linking insulin resistance and lipid metabolism disorders, and may regulate the balance of blood glucose in the body." (PMID 37508126, 2023). "Modern studies have found that ECD has beneficial weight loss, anti-inflammatory, and anti-oxidation effects, and significantly improves decreased insulin sensitivity and glucose and lipid metabolism disorders, especially lipid metabolism in metabolic diseases." (PMID 34366839, 2021). "Therefore, it is of therapeutic significance to target Akt to improve insulin sensitivity for glucose and lipid metabolism disorders treatment." (PMID 30941042, 2019). "A previous study had shown that AQP7 is up-regulated by fasting, low insulin and PPARα and altered expression may be related to lipid metabolism disorders." (PMID 31272371, 2019). "Rehmanniae could be applicable for the treatment of DR by improving function of pancreas islet cells, reducing resistance level of blood insulin, adjusting the balance of cellular glucose, and improving lipid metabolism disorder." (PMID 31061670, 2019).
lipid metabolism disorders (continued). "The findings of the present study demonstrated that moderate amounts of HAS could significantly reduce serum GSP and GHb levels and increase INS levels in IR model mice, thereby helping to alleviate lipid metabolic disorders, oxidative stress injury, and inflammation." (PMID 39984861, 2025). "Additionally, high BMI may increase the sensitivity of breast cells to insulin, leading to excessive production of insulin antibodies, resulting in a high insulin state, ultimately leading to lipid metabolism disorders." (PMID 39640279, 2024). "On the other hand, short chain fatty acids produced by microbial fermentation of difficult-to-digest carbohydrates could effectively regulate glucose and lipid metabolism disorders through balancing glucose absorption and storage and improving the functions of insulin target tissue." (PMID 35626992, 2022). "Due to the disorder of the biological regulatory function of insulin, T2DM is often accompanied by lipid metabolic disorders." (PMID 40647154, 2025). "Insulin, AST, ALT, TC, TG, and FFAs increased in the serum and liver homogenates of L-KO mice, suggesting more serious liver injury and lipid metabolism disorder." (PMID 36918564, 2023). "In order to explore the effect of FA on glucose and lipid metabolism disorders induced by HFD, mice were intraperitoneally injected with glucose or insulin 1 week before sacrifice for glucose tolerance test or insulin tolerance test." (PMID 35047504, 2021). "Regarding the mechanism by which passive smoking promotes carbohydrate and lipid metabolism disorders and increases the prevalence of IGT and T2DM, some studies have suggested that nicotine affects the function of islet cells and insulin." (PMID 32453705, 2020). "Lipid metabolic disorders stimulate the excessive production of FFA in obese individuals, which decreases insulin-stimulated glucose uptake in the whole body." (PMID 31427967, 2019). "Lipid metabolic disorders stimulate the excessive production of FFA in obese individuals, which subsequently decreases insulin-stimulated glucose uptake in the whole body." (PMID 29291086, 2017). "Furthermore, NCNL can significantly improve the glucose and lipid metabolism disorders and affect amino acid metabolism through PI3K-Akt, insulin resistance, and prolactin pathways to achieve its therapeutic effect." (PMID 34221092, 2021). "A relatively high dose of insulin was required and could not be completely discontinued; after insulin treatment, glucose and lipid metabolic disorders and visual acuity were improved." (PMID 41890190, 2026). "CJE could inhibit gluconeogenesis and promote glycogen synthesis through the insulin-mediated IRS1-PI3K-Akt-FoxO1/GSK 3β pathway and increase glucose transport through the AMPK-GLUT4 pathway, thereby regulating glucose and lipid metabolism disorders in T2DM mice." (PMID 40077469, 2025). "Studies have found that in the state of IR, the insulin signaling pathway is damaged, and PI3K and AKT phosphorylation is significantly inhibited, which stimulates liver fat deposition and gluconeogenesis, leading to liver glucose and lipid metabolism disorder." (PMID 36265585, 2022). "Furthermore, in Lin's study, salvianolic acid B inhibited the LPS/TLR4 signalling pathway by inhibiting the abundance of gram-negative bacteria and improving insulin sensitivity and lipid metabolism disorder in HFD mice." (PMID 34686199, 2021).
diabetic cardiomyopathy (135 papers, 2010 to 2026). Diabetic cardiomyopathy is a disorder of the heart muscle in people with diabetes. "The insulin–heart axis is pathologically associated with the development of heart diseases, primarily cardiac hypertrophy and diabetic cardiomyopathy." (PMID 39125938, 2024). "MIR195 can contribute to diabetic cardiomyopathy by affecting systemic inflammation, insulin sensitivity, and causing liver damage." (PMID 38256676, 2024). "The pathophysiology of DM is complex, involving insulin resistance, β-cell dysfunction, and associated cardiovascular complications including diabetic cardiomyopathy (DCM) and cardiovascular autonomic neuropathy (CAN)." (PMID 39742220, 2024). "Metabolic characterizations have indicated that impaired insulin metabolic signaling is a contributing pathophysiological abnormality associated with diabetic cardiomyopathy." (PMID 36890516, 2023). "A previous study reported that FOXO is activated by HFD and that diabetic cardiomyopathy, characterized by cardiac hypertrophy, is caused by insulin resistance due to FOXO activation." (PMID 29016649, 2017). "These metabolites alter insulin signaling pathways, which in turn causes diabetic cardiomyopathy." (PMID 40100371, 2025). "While the current study focuses on elucidating TRA’s cardioprotective effects through modulation of pyroptosis and the GPX3/Nrf2 axis, future work will systematically explore its regulatory roles in lipid metabolism and insulin signaling-two central pathogenic drivers of diabetic cardiomyopathy." (PMID 40529489, 2025). "Similarly, miR-22 has been associated with adipose tissue mass, insulin sensitivity, and glucose homeostasis and diabetic cardiomyopathy." (PMID 34425916, 2021). "This pathway and the corresponding L-type Ca2+ entry is defective in insulin-deficient and resistant states which might contribute to the cardiac contractile dysfunction in diabetic cardiomyopathy." (PMID 30787881, 2019). "Preceding the predominant utilisation of lipids that is a hallmark of diabetic cardiomyopathy, the early phase of metabolic remodelling may indeed be characterised by a heightened sensitivity to insulin that promotes glucose uptake and usage." (PMID 26684450, 2016). "This information would be of clinical importance, because it might strongly justify and encourage the use of therapeutic interventions, including drugs capable of improving insulin sensitivity, with the aim of reducing the risk for diabetic cardiomyopathy." (PMID 20950415, 2010). "Indeed, several reports have demonstrated that the expression of Vegfa mRNA and protein are decreased in the myocardium of diabetic, insulin-resistant animals, and in diabetic patients, and have been associated with vascular abnormalities in the diabetic heart and with diabetic cardiomyopathy." (PMID 29753320, 2018). "The 613 differentially expressed lipids between Ros150 and You150 were significantly enriched in sphingolipid metabolism, long-term depression, diabetic cardiomyopathy, insulin secretion, and fatty acid degradation pathways." (PMID 40774172, 2025). "Inhibit sodium-glucose co-transporter 2 (SGLT2), improve insulin sensitivity, reduce myocardial fibrosis; reduce oxidative stress and enhance mitochondrial function, improving cardiac function in diabetic cardiomyopathy." (PMID 40352456, 2025). "Of the two pathways related to cardiac function, i.e. diabetic cardiomyopathy and insulin signaling pathways, eight genes were involved in cardiac growth." (PMID 40341377, 2025). "This increased fission leads to higher ROS production and impaired insulin signaling, further exacerbating diabetic cardiomyopathy." (PMID 40598681, 2025). "The development of diabetic cardiomyopathy can be triggered by the metabolites of gut microbiota, which control inflammation, insulin resistance, autophagy, oxidative stress, and apoptosis." (PMID 40100371, 2025).
diabetic cardiomyopathy (continued). "Diabetic cardiomyopathy is characterized by a number of pathophysiological abnormalities, one of which is impaired cardiac insulin metabolic signaling, which is most prevalent in patients with T2D." (PMID 38610175, 2024). "Increased diacylglycerols and ceramides have also been observed in diabetic models and contribute to impaired insulin signaling and diabetic cardiomyopathy." (PMID 39256891, 2024). "What strengthens our results is the similarity to the insulin response in postnatal CMs and the possibility of using our model to modulate metabolic disorders such as diabetic cardiomyopathy." (PMID 39125765, 2024). "HERV-K expression was positively correlated with genes involved in oxidative phosphorylation and diabetic cardiomyopathy and negatively correlated with genes involved in Hippo and insulin signaling, cellular senescence, and relaxin signaling." (PMID 39033293, 2024). "Involvement of post‐translational modifications in insulin resistance and impaired Ca2+ handling impacts diabetic cardiomyopathy." (PMID 38494853, 2024). "D. officinale showed a decrease in the amount of serum fasting insulin (FINS) in mice with diabetic cardiomyopathy." (PMID 37396948, 2023). "SLC30A7 is involved in the regulation of insulin secretion and in the regulation of diabetic cardiomyopathy progression by influencing muco-mitochondrial coupling in hyperglycemic cardiomyocytes." (PMID 36674633, 2023). "PTMs not only affect the progression of CVDs but also regulate CVD-related syndromes, such as insulin sensitivity and diabetic cardiomyopathy." (PMID 35855865, 2022). "The pathogenesis of diabetic cardiomyopathy is complex and multifactorial, and it is widely accepted that its mechanisms include oxidative stress, inflammation, insulin resistance, apoptosis, and autophagy." (PMID 36091756, 2022). "In this review, we discuss how cardiac energy metabolism is altered in diabetic cardiomyopathy and the impact of cardiac insulin resistance on the contribution of glucose and fatty acid to overall cardiac ATP production and cardiac efficiency." (PMID 34831481, 2021). "Insulin resistance into the heart has been considered to favor myocardial contractile dysfunction and to be involved in the pathophysiology of diabetic cardiomyopathy." (PMID 33608002, 2021). "In this study, we show that impaired calcium homeostasis due to cardiac insulin resistance contributes to the development of diabetic cardiomyopathy." (PMID 32367034, 2020). "Vit D helps reduce diabetic cardiomyopathy not only by improving blood sucrose and insulin levels but also by downregulating advanced glycation end product formation and hexosamine pathways in heart tissues." (PMID 33362559, 2020). "While this review has focused on the occurrence of cardiac dysfunction in insulin-dependent (type 1) diabetes, impaired insulin signaling has been suggested as a contributory mechanism in the pathogenesis of both types of diabetic cardiomyopathy." (PMID 32244448, 2020). "Relaxin-3 is a bioactive peptide with a structure similar to insulin, which has been reported to be effective in diabetic cardiomyopathy models in vivo and in vitro." (PMID 33584279, 2020). "Fang and Ma showed that SIRT1 expression was reduced in a mouse model of diabetic cardiomyopathy resulting in both compromised insulin signaling and mitochondrial dynamic abnormity." (PMID 31076562, 2019). "In contrast, diabetic cardiomyopathy is rather caused by decreased glucose uptake (due to decreased GLUT4 membrane translocation upon insulin stimuli) and side-effects of the elevated insulin levels—decreased nitric oxide and increased intracellular Ca2+." (PMID 31466420, 2019). "Our data is supported by previous studies showing that glucagon antagonism mitigates diabetic cardiomyopathy in Leprdb/db diabetic mice, coinciding with improved whole body insulin signalling." (PMID 30626440, 2019).
diabetic cardiomyopathy (continued). "The expression of SIRT1 was shown to be reduced in a mouse model of diabetic cardiomyopathy and resulted in both compromised insulin signaling and mitochondrial dynamic abnormity." (PMID 30071860, 2018). "A previous study reported that sustained activation of Foxo1 or Foxo3 leads to diminished insulin responsiveness and impaired glucose metabolism in cardiac myocytes, and Foxo1 activation triggers diabetic cardiomyopathy through downregulation of Irs1 in mice." (PMID 28887535, 2017). "It is known that EGFR activation is a key component in diabetic damage; it involves in insulin sensitivity, and leads to diabetic cardiomyopathy." (PMID 28427241, 2017). "Diabetic cardiomyopathy is a myocardial disease triggered by impaired insulin signalling, increased fatty acid uptake and diminished glucose utilisation." (PMID 26684450, 2016). "A host of changes have been described in diabetic cardiomyopathy, characterized by cardiac hypertrophy, inflammation, fibrosis, and apoptosis due to altered insulin signaling and calcium handling." (PMID 26242235, 2015). "Diabetic cardiomyopathy is characterized by increased free fatty acid oxidation in parallel with cardiomyocyte insulin resistance." (PMID 26242235, 2015). "For example, in early stage diabetic cardiomyopathy, mitochondrial stress is commonly observed, along with disrupted calcium homeostasis, elevated calcineurin, and insulin resistance." (PMID 25216282, 2014). "Results presented here demonstrate that mTORC1 inhibition with PRAS40 prevents the development of diabetic cardiomyopathy and improves hepatic insulin sensitivity, revealing a new target for treatment of T2DM and associated cardiomyopathy." (PMID 24408966, 2014). "In diabetic cardiomyopathy, the upregulation of glycophagy may reduce the sensitivity of cardiomyocytes to insulin and aggravate myocardial injury." (PMID 41522193, 2026). "In diabetic cardiomyopathy, the upregulation of glycophagy may reduce the sensitivity of myocardial cells to insulin, thereby exacerbating myocardial damage." (PMID 41522193, 2026). "Functional enrichment analysis showed that these hub genes were significantly enriched in cardiac function (e.g. diabetic cardiomyopathy and insulin signaling pathway), signaling (mTOR signaling pathway), oxygen metabolism (thermogenesis and oxidative phosphorylation), autophagy, and diseases." (PMID 40341377, 2025). "Insulin signaling transduction genes and their roles in diabetic cardiomyopathy." (PMID 40747301, 2025). "Notably, pathways such as glycerophospholipid metabolism have been identified to modulate insulin resistance and lipid metabolism, thereby mitigating cardiac damage in models of diabetic cardiomyopathy." (PMID 38708085, 2024). "In the pathogenesis of diabetic cardiomyopathy-induced HF, the increased mitochondrial fission is mainly ascribed to the elevated blood glucose levels resulting from insulin resistance or insufficient insulin secretion, leading to disruption of the mitochondrial network structure." (PMID 38489673, 2024). "The principal finding of the present study is that carbonylation oxidative stress from hearts of STZ induced diabetic rats with established diabetic cardiomyopathy; Rb1 and insulin treatment increased SOD activity and reduced MDA adducts in cardiac muscle of STZ diabetic rats." (PMID 38961333, 2024). "Another major finding of the present study is that phosphorylation RyR2 at S2808 by carbonylation oxidative stress is important mechanisms of diabetic cardiomyopathy; Rb1 and insulin treatment is more efficacious way to reduce the process of phosphorylation RyR2." (PMID 38961333, 2024). "Since the beneficial actions of sarpogrelate treatment in diabetic cardiomyopathy were similar to those of insulin treatment, the effects of insulin treatment on subcellular remodeling in diabetic animals were also studied for the purpose of comparison with sarpogrelate." (PMID 39057635, 2024).